RAP1GAP2 (RAP1 GTPase activating protein 2)
Description:
GTPase activator for the nuclear Ras-related regulatory protein RAP-1A (KREV-1), converting it to the putatively inactive GDP-bound state.
Synonyms: GARNL4; KIAA1039; RAP1GA3
Tractability: Antibody: its Gene Ontology location is reachable by antibodies, with high confidence. PROTAC: ubiquitination databases record sites on it; its protein half-life has been measured.
Gene: Protein-coding gene on chromosome 17 (2,755,705 to 3,037,741, forward strand). Ensembl gene ENSG00000132359.
Subcellular location: Cytoplasm; Cytoplasm, perinuclear region
Subcellular location (Human Protein Atlas): Cytosol; Nuclear membrane; Flagellar centriole; Perinuclear theca; Principal piece
Pathways (Reactome):
Immune System: Rap1 signalling
Gene Ontology:
Molecular function: GTPase activator activity; protein binding
Biological process: regulation of cell size; adaptive immune response; regulation of small GTPase mediated signal transduction
Cellular component: centrosome; cytosol; plasma membrane; axon; cytoplasm; neuron projection; perinuclear region of cytoplasm
Genetic constraint (gnomAD): Loss-of-function variants: 26 observed, 83.36 expected, observed/expected ratio (o/e) 0.31, 90% interval 0.23 to 0.43. The upper end of that interval is the gene's LOEUF score, 0.43, which puts it in group 1 of 6, group 1 being the genes least tolerant of losing a copy. Missense variants: 768 observed, 923.94 expected, observed/expected ratio (o/e) 0.83, 90% interval 0.78 to 0.88. Synonymous variants: 368 observed, 364.55 expected, observed/expected ratio (o/e) 1.01, 90% interval 0.93 to 1.1.
Homologues: Orthologues: chimpanzee RAP1GAP2 (98% identical), macaque RAP1GAP2 (97% identical), guinea pig RAP1GAP2 (94% identical), rat Rap1gap2 (93% identical), dog RAP1GAP2 (92% identical), mouse Rap1gap2 (92% identical), pig RAP1GAP2 (92% identical), rabbit RAP1GAP2 (88% identical), tropical clawed frog rap1gap2 (76% identical), zebrafish rap1gap2b (58% identical), zebrafish rap1gap2a (46% identical), Drosophila melanogaster RapGAP1 (38% identical), and 2 more. Paralogues in human: RAP1GAP (48% identical), SIPA1L3 (33% identical), SIPA1L2 (32% identical), SIPA1L1 (31% identical), GARNL3 (25% identical), SIPA1 (25% identical).
Diseases named in the same sentence as RAP1GAP2 in open-access papers:
RAP1GAP2 is named in the same sentence as 11 diseases in open-access papers, as found by Europe PMC text mining. Sharing a sentence is not in itself a finding about the gene and the disease. The quoted sentences say what the papers report.
asthma (1 paper, 2022). "In the male-only analysis, the CD8T cells differentially methylated RAP1GAP2 gene has been associated with asthma, an autoimmune, stress-related syndrome." (PMID 36192377, 2022).
leukemia (1 paper, 2023). A malignant (clonal) hematologic disorder, involving hematopoietic stem cells and characterized by the presence of primitive or atypical myeloid or lymphoid cells in the bone marrow and the blood. "Besides Mecom, other integrations near or within leukemia-related proto-oncogenes or tumor suppressors were found within the top 10 most abundant in the expanded clones (Anxa659, Nemf or Sdccag1, Ldhc, Nbea, Rap1gap2, Iqgab1, Cript, Kalrn, Pkig, and Ubr2)." (PMID 37566057, 2023).
Obesity (1 paper, 2025). Accumulation of substantial excess body fat. "RAP1GAP2 is associated with obesity-related traits, further emphasizing the link between metabolism and long-term health." (PMID 41514760, 2025).
infection (2 papers, 2022 to 2023). The state of being infected such as from the introduction of a foreign agent such as serum, vaccine, antigenic substance or organism. "In accordance with these observations, analyses of RNA-seq data obtained after 24 and 48 h of infection revealed that cardiomyocyte infection caused an increase in gene expression of Epac1 and Rap1b, while Rap1GAP2, a protein that induces inactivation of Rap1b, presented a decreased expression." (PMID 38156015, 2023). "The expression of the immune-related gene Rap1GAP2 has been modulated in channel catfish (Ictalurus punctatus) after the infection with Flavobacterium columnare." (PMID 36672855, 2022).
RAP1GAP2 also shares sentences with these, for which no sentence is quoted: arrhythmogenic right ventricular cardiomyopathy (1 paper); autoimmune (1); Chagas cardiomyopathy (1); dilated cardiomyopathy (1); hypertrophic cardiomyopathy (1); leiomyoma (1); leiomyosarcoma (1).